IL3 (interleukin 3)
Diseases named in the same sentence as IL3 in open-access papers (continued):
Sharing a sentence is not in itself a finding about the gene and the disease.
viral pneumonia (1 paper, 2023). Inflammation of the lung parenchyma that is caused by a viral infection. "IL-3 regulates the innate and adaptive function of pDCs during viral pneumonia by either promoting their recruitment into the airways or by improving their capacity to prime T cells." (PMID 36911737, 2023). "During viral pneumonia, IL-3 improves innate antiviral immunity by promoting plasmacytoid dendritic cells (pDC) recruitment into the lungs." (PMID 36911737, 2023). "The reduced plasma IL-3 levels observed in septic patients with viral pneumonia or in patients with severe SARS-CoV-2 infections might therefore reflect the lymphopenic state observed in these patients." (PMID 36911737, 2023). "Considering that airway epithelial cells are one of the main orchestrators of pulmonary immune responses, and have been identified to express the IL-3 receptor, IL-3 may also protect against viral pneumonia by directly stimulating pulmonary epithelial cells." (PMID 36911737, 2023). "In mice, CLP Il-3-/- mice were more susceptible than CLP WT mice to viral pneumonia although murine pDCs do not express the α chain of the IL-3 receptor indicating that the antiviral function of IL-3 seems to work through different ways." (PMID 36911737, 2023). "Therefore, we wondered whether IL-3 might also protect septic patients from viral pneumonia by directly improving the antiviral function of pDCs." (PMID 36911737, 2023). "Indeed, septic patients with either primary (SARS-CoV-2) lung viral infections or viral reactivation (HSV-1) showed similarly decreased plasma IL-3 levels when compared to septic patients without viral pneumonia." (PMID 36911737, 2023).
tumor (143 papers, 2002 to 2026). "Overall, cells secreting CCL3 were linked to reduced tumor growth, and treatments like the IL3 vaccine or bolus rCCL3 therapy showed promise in reducing tumor growth." (PMID 41153795, 2025). "Previous research has indicated that tumour-associated leukocytes from patients with metastatic lymph nodes secreted higher levels of IL-3 and IL-5." (PMID 36980567, 2023). "In our study, comprehensive qPCR analysis of tumor samples revealed significant differences between the experimental groups regarding the MC-associated markers Cpa3, Il-3 as well as the MC-proteases (Mcpt1, 2, 4, 5, 6, 7)." (PMID 37686555, 2023). "Introduction of IL-3/anti-IL-3 antibody complexes triggered basophilia and infiltration of T cells which were associated with tumor rejection." (PMID 35159247, 2022). "Studies have shown that interleukins and their receptors are closely associated with tumor metastasis; for example, IL-3 and IL-7R in different modules can promote both the proliferation and metastasis of tumors." (PMID 28628609, 2017). "These therapies not only cause tumor regression, but also alleviate immunosuppression and release tumor-associated antigens taken up by IL-3-activated macrophages, which contribute to the enhanced anti-tumor immune response." (PMID 23441198, 2013). "Several studies have demonstrated that macrophages are the prime cells responsible for the IL-3-associated anti-tumor T cell response." (PMID 23441198, 2013). "Research indicates that increased eosinophil infiltration within CRC tumors, potentially influenced by IL-5 and IL-3, may be linked to a better prognosis, suggesting a possible anti-tumor effect of these cells." (PMID 40500799, 2025). "Tumor-associated endothelial cells produce IL-3, a pro-inflammatory cytokine." (PMID 40149564, 2025). "After being secreted by activated T cells, monocytes, and/or tumor-associated stromal cells, IL-3 could induce a concomitant increase in the percentage of both Foxp3+ Tregs and IL-2 secreting Th cells in a dose-dependent manner." (PMID 33868318, 2021). "Downregulation of IL-3 signaling pathway is associated with impairment of DC maturation and activation of adaptive immune response, and hence could be associated with diminished ability of tumor eradication, and poor survival rates." (PMID 33312958, 2020). "The differentiation of megakaryocytes to platelets could be triggered by the tumor-associated inflammatory mediators, such as IL-1, IL-3, and IL-6 that accelerate tumor cell growth and dissemination; in addition, platelets cooperate to protect circulating cancer cells from the immune system." (PMID 31261762, 2019). "These IL3-Lamp2B (IL3L) exosomes showed enhanced tumor targeting and therapeutic efficacy in preclinical models." (PMID 41181109, 2025). "Together, these results suggest that TTC7A-ALK is a potent oncogenic driver capable of promoting IL-3-independent proliferation, tumor growth, and activation of key signaling pathways, and it remains sensitive to crizotinib inhibition." (PMID 40054123, 2025). "By supporting endothelial cell survival and proliferation, as well as promoting the differentiation of hematopoietic progenitor cells, IL-3 enhances tumor angiogenesis and sustains vascular networks necessary for tumor growth." (PMID 41373619, 2025). "In the tumor microenvironment, various factors beyond M-CSF and GM-CSF have been shown to regulate macrophage maturation, including IL-3, IL-10, TGF-β, and physical factors such as extracellular matrix and hypoxia." (PMID 38424542, 2024). "IL-3 is also expressed by activated tumour-infiltrating lymphocytes, Tregs and tumour-derived endothelial cells." (PMID 38903497, 2024). "IL-10 is an anti-inflammatory cytokine that plays a crucial role in tumor killing and inhibits the production of IFNg, IL-2, IL-3, and TNFα." (PMID 37445686, 2023).
tumor (continued). "For example, in a mouse model, imatinib-laden IL3-exosomes significantly reduced the tumor burden when compared to imatinib-free IL3-exosomes, regular exosomes loaded with imatinib, and imatinib alone (p <0.0005)." (PMID 38260856, 2023). "The release of protein material through necrotic changes as well as cytokines such as interleukin‐5 (interleukin [IL]‐5), IL‐3 and eotaxin‐1 produced by tumour or host inflammatory cells attract eosinophils to neoplastic tissue." (PMID 35654102, 2022). "IL-3 was originally described as a haematopoietic factor; however, IL-3, mainly released by tumour-infiltrating lymphocytes (TILs), acts as a proinflammatory and proangiogenic cytokine." (PMID 36010912, 2022). "Tumours from animals treated with IL-3 displayed a significant increase in PAS-positive/CD31-negative vessels, corresponding to the vascular network built by tumour cells and denoted as VM." (PMID 36010912, 2022). "M2 macrophages have pro-tumor effects and promote tumor growth and immune evasion by inducing angiogenesis and producing anti-inflammatory cytokines such as IL-3, IL-10, and TGF-β11–13." (PMID 35136176, 2022). "In cases where it is triggered by neoplasms, IL-5, a growth factor selective for the eosinophil lineage, as well as various cytokines such as IL-3 and GM-CSF, are produced by the tumors." (PMID 34741855, 2021). "Intratumoral injection of adenoviral interleukin-3 provided a more significant tumor growth delay than radiation alone." (PMID 34576217, 2021). "Interleukin-3 (IL-3) acts as an autocrine factor for tumor–endothelial cells (TEC), and exerts pro-angiogenic paracrine action via extracellular vesicles (EVs)." (PMID 33040091, 2020). "In contrast to tumor-infiltrating APCs, pathways related to the positive regulation of immune and defense response, including IL-8/IL-6/IL-3/CXCR4 signaling, TREM1 signaling and leukocyte extravasation pathways were downregulated in I-MDSCs." (PMID 33312958, 2020). "Tumour cells can secrete platelet agonists to induce platelet aggregation, which results in thrombocytosis by producing thrombopoietic cytokines such as interleukin (IL)-1, IL-3, IL-11, and particularly tumour-derived IL-6." (PMID 32312252, 2020). "GM-CSF and IL-3 are both known to stimulate tumor cell proliferation, so their direct effects on tumor growth cannot be excluded." (PMID 33013879, 2020). "Tumor cells in this model exhibit abnormally stable expression of IL-3 mRNA as part of an oncogenic autocrine loop." (PMID 32545247, 2020). "IL-3 is a multipotent hematopoietic growth factor produced by activated T cells, monocytes/macrophages and stroma cells, which was shown to promote tumor angiogenesis." (PMID 33028392, 2020). "The correct sentence should be: Tumor growth leads to the increased production of inflammatory cytokines and growth factors (mainly IL-1, IL-3, IL-6, IL-11, IL-23, and TNF-), and this perpetual process ensures immortality." (PMID 32293548, 2020). "Tumor cells produce cancer-related inflammatory mediators, such as tumor necrosis factor-α, interleukin-3 (IL-3), and IL-6." (PMID 31286873, 2019). "In tumor models, the siRNA-loaded IL3-EVs also displayed efficient gene silencing, leading to delayed tumor growth." (PMID 31754377, 2019). "IL-9 activates innate immune cells like mast cells, contributing to tumor growth prevention, and in addition to Th9 cell-derived IL-3, induction of adaptive anti-cancer responses that favor DCs survival has been reported in various cancers." (PMID 31861351, 2019). "The results showed that IL-3, IL-6, and IL-10 were differentially expressed in splenocytes from tumor bearing WT mice compared with tumor-bearing IRF-8−/−, naïve WT and naïve IRF-8−/− mice." (PMID 29438283, 2018). "Overall, IL-3, present in the tumor microenvironment, can contribute to tumor growth via paracrine and autocrine mechanisms." (PMID 29238040, 2018).
tumor (continued). "Platelets can accumulate following the stimulation of megakaryocytes by inflammatory mediators that are released by the tumor or its microenvironment, such as interleukin (IL)-1, IL-3 and IL-6." (PMID 28489884, 2017). "It has been shown that signals emanated by IL-3 are crucial for tumor cell proliferation and migration and that blockage of IL-3 can prevent both tumor angiogenesis and growth." (PMID 28410543, 2017). "The v-HA-Ras-transformed V2D1 murine tumor mast cells constitutively produces IL-3, resulting in autocrine stimulation, proliferation and survival." (PMID 25749030, 2015). "IL-3 is mostly secreted by activated T-cells and enhances the development of tumor-reactive cytotoxic cells by a CD4-dependent mechanism." (PMID 25776849, 2015). "It is not fully understood what mechanisms drive eosinophil recruitment to the tumor site, although some tumor cells secrete IL-5 and IL-3 that modulate the differentiation and maturation of eosinophils and mast cells." (PMID 25759690, 2015). "For instance, ENA-78 trended towards increased expression with increasing tumor grade and IL-3 trended towards decreased expression with increasing Her2 overexpression." (PMID 26361584, 2015). "The use of IL-3 has also been reported to enhance macrophage-dependent anti-tumor effects when utilized in combination with cancer gene therapy." (PMID 25776849, 2015). "While the role of IL-3 in cancer is unclear, accumulating evidence suggests that IL-3 is involved in inflammatory and tumor angiogenesis." (PMID 24658545, 2014). "Numerous mechanisms have been postulated and bone marrow stimulation by cytokines secreted by tumor tissues, including granulocyte macrophage-colony stimulating factor (GM-CSF), G-CSF, IL-3 and IL-5, is most commonly reported." (PMID 23420572, 2013). "IL-3 gene expression within tumors leads to host-cell infiltration, particularly by macrophages, slower tumor growth and enhanced immunogenicity." (PMID 23426399, 2013). "Tumor secreting IL-3 recruits more macrophages, polymorphonuclear leukocytes, and T cells into the local microenvironment." (PMID 23441198, 2013). "In a mouse lung carcinoma model, IL-3 enhanced tumor rejection by enhancing cytotoxic effectors through a mechanism that required CD4+ cells." (PMID 23441198, 2013). "In order to form tumors, IL-3-generated immunity was compromised by the inoculation of a larger number of IL-3 expressing tumor cells except the experiment in SCID mice." (PMID 23441198, 2013). "The involvement of T cells in HSV-sr39tk/GCV combined IL-3 therapy was further demonstrated by the result that the anti-tumor effect was reduced in SCID mice." (PMID 23441198, 2013). "Like other inflammatory cells, mast cells are attracted to tumors by various factors, including hypoxia, cellular damage, tissue ischemia and tumor-derived chemoattractants, including stem cell factor, interleukins-3 (IL-3) and IL-4." (PMID 17177999, 2006). "Notably, monocytes in the tumor exhibited significantly enriched GM-CSF and IL-3 signaling, particularly relative to T cell aggregates and the alveolar niche." (PMID 41510257, 2025). "Furthermore, IL-3, produced by TILs and tumor-derived endothelial cells (TECs), plays a multifaceted role in shaping the TME." (PMID 41373619, 2025). "In this study, AFM28 could directly inhibit tumor cell metabolic activity via blockade of IL-3-induced STAT5 phosphorylation." (PMID 40841539, 2025). "In TNBC, IL-3 has been implicated in the recruitment of immunosuppressive myeloid cells, the induction of vascular mimicry (VM), and the promotion of EMT, processes that collectively drive tumor progression and metastatic dissemination." (PMID 41373619, 2025).
tumor (continued). "Inflammatory cytokines, including IL-1α, IL-3, IL-9, and IL-12, are pivotal in amplifying the immune response, particularly in immune surveillance and the clearance of tumor cells, by facilitating the proliferation, differentiation, and activation of immune cells." (PMID 40426998, 2025). "To test the relevance of the proposed ligand-free oligomer structure and assembling mechanisms in vivo, we carried out cellular transformation assays using the IL3-dependent murine lymphoid Ba/F3 cell system with the aim of using these cells to establish tumor xenografts." (PMID 38503739, 2024). "Other protumorigenic cytokines, such as GROα/β/γ, IL-8, and IL-6, are known to be secreted by cancer and stromal cells, whereas IL-2 and IL-3 are secreted from activated T cells to regulate the activity and maturation of immune cells to be able to eliminate tumor cells." (PMID 37759302, 2023). "Interestingly, all these GEP class-associated cytokines (PDGF-AB/BB, MCP-3/CCL7, TNF-β, G-CSF, IL-13, and IL-3) were also among the tumor size-correlated cytokines." (PMID 37509362, 2023). "The immune cells that reside in the tumor microenvironment include lymphocytes, macrophages and polymorphonucleocytes, many of which migrate into the tumor via chemoattractants such as CSF-1, IL-3 and VEGF, and chemokines such as CCL-2." (PMID 35267430, 2022). "IL-3 was able to significantly increase PD-L1 expression in primary tumours, as well as the number of lung lesions and the magnitude of the scattered PD-L1-positive tumour cells in the lung." (PMID 36010912, 2022). "The results show that protein modified exosomes containing IL3-lamp2b and imatinib can specifically target tumor cells in vivo, deliver tumor-suppressive drugs (imatinib or BCR-ABL siRNA) to CML cells, and inhibit the growth of cancer cells in vitro and in vivo." (PMID 34973131, 2022). "All these data sustain the contribution of IL-3 signalling in the tumour microenvironment (TME)." (PMID 36010912, 2022). "Moreover, recruitment of basophils in tumor-draining lymph nodes of pancreatic ductal adenocarcinoma patients has been shown to be activated by T-cell-derived IL-3 to produce IL-4, inducing a tumor-promoting Th2 inflammation." (PMID 33418996, 2021). "On the other hand, the release of inflammatory mediators, such IL-1, IL-3 and IL-6 by cancer cells, triggers the differentiation of megakaryocytes into platelets, thus fueling a vicious cycle where platelets and tumor cells continuously stimulate each-other’s growth." (PMID 34367964, 2021). "On the other hand, cytokine IL-3, is a selective growth factor that stimulates tumor angiogenesis." (PMID 32961854, 2020). "TTP delayed tumor progression by four weeks by enhancing IL-3 mRNA degradation in this model." (PMID 32545247, 2020). "In silico criteria for tumor selection may include the presence of GM-CSF, IL-3 and FLT3-L, ligand expression of chemokine receptors CXCR4, CCR7, and CXCR3 and the absence of very high GM-CSF level." (PMID 33013879, 2020). "Moreover, the role of IL-3 in controlling the proliferation/survival of various target cells, including normal and tumor-derived endothelial cells (TEC), has also been reported." (PMID 33040091, 2020). "In addition, various tumor-related humoral factors and pro-inflammatory cytokines such as interleukin (IL)-1, IL-3 and IL-6 have been shown to stimulate thrombopoiesis in cancer patients." (PMID 33160368, 2020). "Moreover, the cross-resistance to apoptosis emanating from dormant tumor cell-induced overproduction of Interleukin 3 (IL-3) was also upturned using anti-IL-3 antibody." (PMID 31430951, 2019).